ADGRL1 (adhesion G protein-coupled receptor L1)
Description:
Calcium-independent receptor of high affinity for alpha-latrotoxin, an excitatory neurotoxin present in black widow spider venom which triggers massive exocytosis from neurons and neuroendocrine cells. Receptor for TENM2 that mediates heterophilic synaptic cell-cell contact and postsynaptic specialization. Receptor probably implicated in the regulation of exocytosis (By similarity).
Synonyms: KIAA0821; LEC2; LPHN1; CIRL1; CL1; DEDBANP
Tractability: Antibody: UniProt places it where antibodies can reach, with high confidence; UniProt predicts a signal peptide or a membrane-spanning region; its Gene Ontology location is reachable by antibodies, with medium confidence. PROTAC: ubiquitination databases record sites on it; its protein half-life has been measured.
Gene: Protein-coding gene on chromosome 19 (14,147,743 to 14,206,204, reverse strand). Ensembl gene ENSG00000072071.
Subcellular location: Cell membrane; Cell projection, axon; Cell projection, growth cone; Synapse; Presynaptic cell membrane; Synapse, synaptosome
Gene Ontology:
Molecular function: protein binding; cell adhesion molecule binding; G protein-coupled receptor activity; latrotoxin receptor activity; carbohydrate binding; transmembrane signaling receptor activity
Biological process: G protein-coupled receptor signaling pathway; cell surface receptor signaling pathway
Cellular component: plasma membrane; axon; growth cone; membrane; neuron projection; presynaptic membrane; synapse
Genetic constraint (gnomAD): Loss-of-function variants: 30 observed, 134.63 expected, observed/expected ratio (o/e) 0.22, 90% interval 0.17 to 0.3. The upper end of that interval is the gene's LOEUF score, 0.3, which puts it in group 1 of 6, group 1 being the genes least tolerant of losing a copy. Missense variants: 1,506 observed, 1,999.8 expected, observed/expected ratio (o/e) 0.75, 90% interval 0.72 to 0.79. Synonymous variants: 933 observed, 872.77 expected, observed/expected ratio (o/e) 1.07, 90% interval 1.01 to 1.13.
Homologues: Orthologues: dog ADGRL1 (99% identical), pig ADGRL1 (99% identical), macaque ADGRL1 (99% identical), mouse Adgrl1 (98% identical), rat Adgrl1 (98% identical), guinea pig ADGRL1 (98% identical), chimpanzee ADGRL1 (97% identical), rabbit ADGRL1 (85% identical), tropical clawed frog adgrl1 (78% identical). Paralogues in human: ADGRL2 (65% identical), ADGRL3 (54% identical), ADGRL4 (16% identical), ADGRE2 (15% identical), ADGRE5 (15% identical), ADGRB1 (15% identical), ADGRE1 (14% identical), ADGRE3 (14% identical), ADGRB2 (13% identical), ADGRB3 (13% identical), ADGRG6 (13% identical), ADGRA3 (13% identical), and 30 more.
Diseases named in the same sentence as ADGRL1 in open-access papers:
ADGRL1 is named in the same sentence as 34 diseases in open-access papers, as found by Europe PMC text mining. Sharing a sentence is not in itself a finding about the gene and the disease. The quoted sentences say what the papers report.
Obesity (5 papers, 2024 to 2025). Accumulation of substantial excess body fat. "ADGRL1-deficiency increases food intake, impairs glucose sensing and homeostasis, and causes obesity in mice." (PMID 41048440, 2025). "Consistently, we identified a partially inactivating mutation in human ADGRL1/LPHN1 in a patient suffering from obesity." (PMID 38664368, 2024). "Recently, I read with interest the research article entitled ‘Dysfunction of the adhesion G protein-coupled receptor latrophilin 1 (ADGRL1/LPHN1) increases the risk of obesity’1 published in Signal Transduction and Targeted Therapy." (PMID 39080020, 2024). "ADGRL1 deficiency in the hypothalamus causes insulin resistance, obesity and impairs glucose sensing in mice." (PMID 37712955, 2024). "A genome-wide scan suggests that the ADGRL1 locus on chromosome 19 (19p13) is associated with human obesity." (PMID 37712955, 2024). "For example, hyperinsulinaemia, insulin resistance and reduced physical activity appear to have contributed to obesity in mice deficient in ADGRL1 in the VMH because hyperphagia was observed after the development of obesity in these mice." (PMID 37712955, 2024). "Given the involvement of the VMH in sex-dependent regulation of energy balance, we determined whether ADGRL1 deficiency in the VMH produced obesity in female mice." (PMID 37712955, 2024). "To answer whether oestrogen is responsible for protecting the ADGRL1-deficient mice from obesity, we performed ovariectomy in these mice and their littermate controls." (PMID 37712955, 2024). "In addition, the Adgrl1-deficient mice had impaired feeding responses to glucose and fasting coupled with abnormal glucose sensing and decreased physical activity before development of obesity and hyperglycaemia." (PMID 37712955, 2024). "It is likely that the local adipocyte ADGRL1 is involved in glucose signaling pathways and pathogenesis of type 2 diabetes and obesity." (PMID 41048440, 2025). "The Adgrl1 KO mice exhibited obesity and hyperphagia was observed when they were about 12 weeks of age." (PMID 37712955, 2024). "Our data highlight ADGRL1/LPHN1 as a novel regulator of food intake and energy balance, and its dysfunction may contribute to the onset or progression of obesity." (PMID 38664368, 2024). "Targeting ADGRL1 may introduce a new class of drugs for the treatment of type 2 diabetes and obesity." (PMID 37712955, 2024). "According to this, obese people’s greater insulin secretion is correlated with increased ADGRL1 expression in their pancreatic islets; as a result, reducing ADGRL1 expression may prevent obesity from developing." (PMID 39126035, 2024). "Our findings demonstrated that lack of ADGRL1 in the hypothalamus or whole-body causes obesity and features of type 2 diabetes in mice." (PMID 39080020, 2024). "Therefore, our findings from the ADGRL1-deficient mouse models provide proof-of-principle to establish the contribution of ADGRL1 to human obesity." (PMID 37712955, 2024). "We found that ADGRL1 deficiency alone did not cause obesity in female mice." (PMID 37712955, 2024). "Targeting ADGRL1 may introduce a new class of drugs for treatment of type 2 diabetes and obesity." (PMID 37712955, 2024). "Future studies are required to address whether or how ADGRL1 function is regulated by glucose, insulin, leptin, and different diets in widely used mouse models of the metabolic syndrome such as db/db, ob/ob and diet-induced obesity models." (PMID 37712955, 2024). "Further studies will determine whether ADGRL1 is regulated by changes in food intake, physical activity, and/or by fluctuations in blood glucose levels to establish its role in common (multifactorial/polygenic) obesity versus rare (monogenic) forms of obesity." (PMID 39080020, 2024). "Therefore, ADGRL1 appears to be a therapeutic target for treatment of obesity and type 2 diabetes." (PMID 39080020, 2024).
neuroblastoma (4 papers, 2018 to 2025). Neuroblastoma (NB) is the most common solid, extracranial childhood tumor. "PFOA was previously shown to solubilize the NTF of a recombinant ADGRL1 construct expressed in neuroblastoma cells, while leaving the CTF in the membrane." (PMID 40711170, 2025). "Mobilization of Ca2+ from intracellular stores was detected using a membrane-permeable Ca2+-sensing dye, Fluo-4 AM, which was loaded into the ADGRL1-transfected or control neuroblastoma cells, where the dye was hydrolyzed and entrapped in the cytosol." (PMID 39998090, 2025). "We demonstrate that at low concentrations (≤100 μM) PFOA does not adversely affect ADGRL1-expressing neuroblastoma cells or inhibit LTXN4C binding." (PMID 40711170, 2025). "Thus, the bulk of Ca2+ that is indirectly and relatively slowly released from the ER by TG or by ADGRL1-mediated signaling could be taken up by MC in neuroblastoma cells and frog NMJs but not in smaller mouse NMJs." (PMID 39998090, 2025).
epilepsy (3 papers, 2024 to 2026). A brain disorder characterized by episodes of abnormally increased neuronal discharge resulting in transient episodes of sensory or motor neurological dysfunction, or psychic dysfunction. "In humans, ADGRL1 haploinsufficiency is associated with cranial malformations, attention deficit/hyperactivity disorder, developmental delay, autism spectrum disorders, intellectual disability, and epilepsy." (PMID 40711170, 2025).
acute myeloid leukemia (2 papers, 2021 to 2022). Acute myeloid leukemia (AML) is a group of neoplasms arising from precursor cells committed to the myeloid cell-line differentiation. "Acute myeloid leukemia cells (AMLs) express ADGRL1/LPHN1 (adhesion G protein-coupled receptor L1/latrophilin 1), which help to facilitate the secretion of galectin-9 (the immune suppressor that lacks a secretory domain) and TIM3 (T-cell immunoglobulin and mucin domain containing protein 3)." (PMID 35723340, 2022).
dementia (1 paper, 2025). Loss of intellectual abilities interfering with an individual's social and occupational functions. "Although PFOA can cross the blood–brain barrier, its levels in the brains of Australian dementia patients (0.002 μM) were 8–10-fold lower than in the serum (0.016 μM), indicating a potentially low risk of neurological disorders and ADGRL1 dysfunction." (PMID 40711170, 2025).
hyperglycaemia (1 paper, 2024). "The ADGRL1-deficient mice exhibited fasting hyperglycaemia on the 24th week following ADGRL1 knockdown." (PMID 37712955, 2024).
Insulin resistance (1 paper, 2024). Increased resistance towards insulin, that is, diminished effectiveness of insulin in reducing blood glucose levels. "Lack of Adgrl1 in the VMH in mice caused fasting hyperinsulinaemia, enhanced glucose-stimulated insulin secretion and insulin resistance." (PMID 37712955, 2024).
Stroke (1 paper, 2025). Sudden impairment of blood flow to a part of the brain due to occlusion or rupture of an artery to the brain. "Upregulation of ADGRL1, CDK5R1/CDKL3, CHRNB2, and ROR2 genes in post-stroke long-lasting brain fatigue generally supports neuroplasticity, cognitive recovery, and neurogenesis, which are beneficial for rehabilitation." (PMID 40006074, 2025). "The upregulation of ADGRL1, CDK5R1/CDKL3, CHRNB2, and ROR2 gene expression in the context of long-lasting post-stroke brain fatigue can have a mix of positive and negative effects, depending on how these proteins influence brain function, recovery, and energy regulation." (PMID 40006074, 2025).
neurodevelopmental disorder (4 papers, 2019 to 2025). A behavioral and cognitive disorder with onset during the developmental period that involves impaired or aberrant development of intellectual, motor, or social functions. "A recent study revealed that loss-of-function mutations of Lphn1 (ADGRL1) cause major neurodevelopmental disorders in humans and synaptic impairments in mice." (PMID 38684366, 2024).
neurologic disease (3 papers, 2023 to 2025). "If PFOA affects ADGRL1 in real-world conditions, this may be associated with an increased risk of neurological disorders." (PMID 40711170, 2025).
cancer (2 papers, 2019 to 2025). A tumor composed of atypical neoplastic, often pleomorphic cells that invade other tissues. "Among them are genes involved in cell adhesion/migration processes (PEPD), migratory potential of cancer cells (ACTN1), ECM (LTBP2, PRG4, ADGRL1, CD9), or in metabolic processes (LDHD, ALDH7A1), as well as proto-oncogenes or their ligands/inhibitors (FYN, PPP1R13L)." (PMID 30838002, 2019).
hematological malignancies (1 paper, 2021). "First, we wanted to verify whether there is a reciprocal relationship between the gene expression of ABCB1 and ADGRL1, which we found in the AML cell lines SKM-1 and MOLM-13 in samples from patients with hematological malignancies." (PMID 34298843, 2021).
ADGRL1 also shares sentences with these, for which no sentence is quoted: infection (3 papers); attention deficit-hyperactivity disorder (2); autism (2); autism spectrum disorder (2); tumor (2); type 2 diabetes (2); acute monocytic leukemia (1); asthma (1); breast carcinoma (1); congenital heart defects (1); COVID-19 (1); developmental delay (1); endometriosis (1); Intellectual disability (1); leukaemia (1); metabolic syndrome (1); monocytic leukaemia (1); myelodysplastic syndrome (1); neuropathy (1); prostate carcinoma (1); schizophrenia (1); status epilepticus (1).